SIRT1 (sirtuin 1)
Diseases named in the same sentence as SIRT1 in open-access papers (continued):
Sharing a sentence is not in itself a finding about the gene and the disease.
Hyperglycemia (continued). "SIRT1 expressions were markedly low in hyperglycemia-exposed podocytes." (PMID 30674969, 2019). "Here, we report that hyperglycaemia promoted the production of ROS and that the activation of Sirt1 by butein may suppress ROS in NP cells." (PMID 31583043, 2019). "The present study demonstrates the expanded role of SIRT1 as a key regulator of endothelial cell homeostasis and identifies SIRT1 as a specific modulator of the angiogenic activity of endothelial cells against hyperglycemia." (PMID 31068817, 2019). "Once the SIRT1 co-factor NAD+ is diminished via hyperglycaemia it may be unable to competitively inhibit the acetylation of RUNX2, allowing an increase of calcification within the patient." (PMID 30696833, 2019). "To further investigate how activation of Sirt1 by butein may affect NP cells, we examined apoptosis in NP cells under conditions of hyperglycaemia." (PMID 31583043, 2019). "As it is well established that hyperglycemia itself decreases SIRT1 expression, metformin may act in two ways, via miR-195 reduction and by improving glycemic control (thus also indirectly improving SIRT-1)." (PMID 30347712, 2018). "Since SIRT1, participates in regulation of glucose homeostasis through regulating hepatic glucose production, lipid metabolism and insulin production, and sensitivity, indicates its potential role to control hyperglycemia in type 2 diabetes." (PMID 30072892, 2018). "In bovine retinal capillary endothelial cells (BRECs), Sirt1 overexpression inhibited the increase in mitochondrial reactive oxygen by diminishing NF-κB expression while depletion of Sirt1 via siRNA presented reduced resistance to ROS induced by hyperglycemia stress." (PMID 28546854, 2017). "In addition, persistent activation of JNK1/2 by multiple factors including hyperglycemia induces extensive SIRT-1 proteasome degradation followed by phosphorylation at Ser47." (PMID 27542238, 2016). "Hyperglycaemia induces endothelial cell death via suppression of SIRT1." (PMID 27561827, 2016). "Taken together, data from the current study thus support the hypothesis that ANM promotes anti-oxidant defense and SIRT-1 stability in hyperglycemia-induced dermal fibroblasts and endothelial cells that minimize cellular senescence and growth arrest." (PMID 27542238, 2016). "The present study was designed to elucidate whether CHS protected against hyperglycemia-induced ROS explosion and Ca2+ overload by stimulating the expression of Homer1a and the involvement of SIRT1/ERK1/2 signaling in vivo and in vitro." (PMID 26648253, 2015). "Based on these data, it’s speculated that SIRT1 might be partly reduced by hyperglycemia, which is a common characteristic between type 1 and type 2 diabetes." (PMID 26489513, 2015). "In conclusion, the present study is the first to clearly highlight that pancreas-specific Sirt1 loss does not result in hyperglycemia, despite having compromised beta-cell function." (PMID 26046931, 2015). "Indeed, it has been shown that metformin is effective in suppressing the deleterious effects of hyperglycaemia in retinal capillary endothelial cells and in the retinas of diabetic animals by modulating the SIRT-1/LKB1/AMPK pathway." (PMID 26064979, 2015). "This re-demonstrated the SIRT1 mediated aging in the ECs in hyperglycemia." (PMID 23342163, 2013).
Hyperglycemia (continued). "In addition, studies have shown that fucoglycan (FO) isolated from brown algae can ameliorate pancreatic β-cell injury and impaired insulin synthesis under diabetic conditions, and improve hyperglycemia, lower expression of SIRT1, PDX-1, and GLP-1R in the pancreas of diabetic mice." (PMID 36632457, 2023). "Therefore, BCs may need to activate SIRT1 and HO-1 to regulate the glucose metabolism to prevent hyperglycemia-induced damage and disease." (PMID 36900446, 2023). "This could be because hyperglycemia is already quite strong in the Sirt1 loss-of-function model, or because we simply did not hit on any enhancing modifiers." (PMID 35435227, 2022). "However, hyperglycemia can directly downregulate SIRT1 deacetylation activity." (PMID 36465704, 2022). "Caloric restriction can increase the expression of Sirt1 and peroxisome proliferator-activated receptor-γ coactivator-1α (PGC-1α), improve mitochondrial function, reduce ROS production, relieve cardiac OS and inflammation caused by hyperglycemia, and play a cardioprotective role." (PMID 35103095, 2022). "In vitro studies found that glucagon-like peptide-1 improves proliferation and differentiation of EPCs via upregulating VEGF generation, and the upregulation of GLP-1 receptor could improve the dysfunction of EPCs in late hyperglycaemia by regulating SIRT1 expression." (PMID 36199064, 2022). "Importantly, because of the resveratrol administration, the mesangial cell damage induced by hyperglycemia-induced oxidative stress was directly alleviated by stimulating the SIRT1 activity, indicating an important role for SIRT1 in mediating the effects of resveratrol." (PMID 35277012, 2022). "In the present study, we found RSV could reverse the down-regulation of SIRT1 by hyperglycemia." (PMID 34177568, 2021). "In this study we’ve investigated whether Hyoscyamus albus nortropane alkaloids reduce hyperglycemia and hyperinsulinemia induced in HepG2 cells through the modulation of oxidative stress, the improvement of glucose metabolism and the regulation of SIRT1/NF-kB/JNK pathway." (PMID 34034759, 2021). "Pancreas-specific SIRT1 deficiency results in lower insulin secretion by β-cells, but is not accompanied by hyperglycemia, suggesting that a compensatory mechanism may exists." (PMID 33806509, 2021). "EGCG pre-treatment considerably upregulated the levels of SIRT1, indicating a crucial role of SIRT1 in EGCG-mediated protection against I/R under hyperglycemia and suggesting that EGCG may be a beneficial dietary supplement for the prevention of diabetic cardiomyopathy." (PMID 34573022, 2021). "Herein, this study was carried out aimed at exploring the pharmacological effects of BAK in the setting of hyperglycemia-induced diabetic cardiomyopathy and elucidate whether SIRT1/Nrf2 signaling is involved in its protective molecular mechanisms both in vivo and in vitro." (PMID 33062139, 2020). "Hyperglycemia-induced decreased SIRT1 activity may potentially suppress ERβ expression." (PMID 31396159, 2019). "Moreover, treatment with miR-34a inhibitor or metformin downregulated miR-34a expression and upregulated SIRT1 expression, indicating that the hyperglycemia-induced modulation of SIRT1 levels and posttranslational modification of eNOS took place through a miR-34a-dependent gene-regulatory mechanism." (PMID 28299324, 2017). "Counter intuitively, the Sirt1-deficient mice did not develop hyperglycemia." (PMID 26046931, 2015). "Another factor implicated in hyperglycemia-induced VSMC calcification is Sirtuin 1 (SIRT1), an NAD+-dependent deacetylase involved in hyperglycemia-induced VSMC transdifferentiation." (PMID 40940776, 2025). "By activating the AMPK/SIRT1/PGC-1α pathway, resveratrol helps eliminate intracellular ROS induced by hyperglycemia and prevents ROS-induced apoptosis in retinal capillary endothelial cells." (PMID 40589740, 2025).
Hyperglycemia (continued). "Its beneficial actions likely stem from reducing oxidative stress, dyslipidemia, and hyperglycemia, potentially through the modulation of HMGB1, SIRT1, and NF-kB pathways." (PMID 39432066, 2024). "Hyperglycemia enhances DNA damage in MSCs; hence, we assessed the expression of DNA repair markers XRCC5, TERF1, CDKN1A, and SIRT1 in ASCs in a diabetic milieu." (PMID 38880916, 2024). "In the bloodstream, hyperglycemia hinders the conversion of NADPH to NAD+, thereby restricting the availability of NAD+ substrates for SIRT1 and limiting its activation." (PMID 37985432, 2024). "The study unveiled significant amelioration of hepatic SIRT1/STAT3 pathway suppression, hyperglycemia, and hepatic gluconeogenesis by melatonin." (PMID 38690282, 2024). "The findings showed a capsaicin-induced increase in sirtuin 1 (SIRT1), a protein that prevents endothelial senescence induced by intermittent hyperglycemia." (PMID 37892544, 2023). "Hyperglycemia-induced dysregulation of DNMT3 and the histone deacetylase (HDAC) SIRT1 have been shown to contribute to cardiac dysfunction in diabetic animals, and activation of SIRT1 has been shown to improve cardiac outcomes." (PMID 37924123, 2023). "Similar to SIRT1, SIRT3 has a defensive role against hyperglycemia by inactivating NF-κB-mediated pathways and downregulating the pro-apoptotic protein Bax." (PMID 35409409, 2022). "SIL promotes the expression of SIRT1, FoxO1, CAT, GPX1 and SOD2 of hyperglycemia Intervention of MC3T3-E1 by reducing intracellular ROS levels and restoring the activity and function of MC3T3-E1, similar to those from some researches." (PMID 36057883, 2022). "Endothelial cells and neurons in the NV chip show sirtuin 1 (SIRT1) downregulation under hyperglycemic conditions, suggesting SIRT1 as a key regulator of hyperglycemia‐induced AD." (PMID 36073820, 2022). "In summary, our research results confirm that hyperglycemia impaired the activity and function of MC3T3-E1 and inhibits bone formation by up-regulating intracellular ROS levels through inhibition of SIRT1/SOD2 signaling pathway." (PMID 36057883, 2022). "It has been reported that liver-specific deletion of Sirt1 upregulates the expression of G6Pase and PCK1 by impairing the mTorc2/AKT/FOXO1 pathway and thus increases hepatic glucose production and chronic hyperglycaemia." (PMID 35132380, 2022). "In contrast, the silencing of SIRT1 resulted in the overexpression of the acetylated form of FOXO3, which potentiated hyperglycaemia-induced oxidative stress induced in renal tubules." (PMID 36232910, 2022). "In HUVECs treated with high glucose, bonding of HuR and Sirtuin 1 (SIRT1) mRNA increases the stability of SIRT1 mRNA, thus inhibits E-selectin release and the activation of ECs induced by inflammation and hyperglycemia." (PMID 34127651, 2021). "Overall, THJ protected the heart from hyperglycemia-induced oxidative stress and inflammation in DCM mice via a mechanism involving SIRT1-mediated antioxidant proteins and suppression of the NLRP3 inflammasome." (PMID 33637069, 2021). "Furthermore, we demonstrated in relevant in vitro models that FKBPL and SIRT-1 proteins are reduced in both the presence of hyperglycaemia and lower oxygen tension (relevant for placental development) that could have adverse effects on trophoblast function and placental development." (PMID 34149611, 2021). "Recent evidence demonstrates the beneficial role of Sirtuin 1 (SIRT1), an NAD+ dependant deacetylase, in improved insulin sensitivity and glucose homeostasis, linking hyperglycaemia and SIRT1 downregulation." (PMID 30696833, 2019).
Hyperglycemia (continued). "Thus the present study was aimed to find out the efficacy of formononetin to control hyperglycemia in high fat diet and low dose of streptozotocin induced type 2 diabetes in Sprague Dawley rats and to find out the effect of formononetin treatment in expression of SIRT1 in pancreatic tissue." (PMID 30072892, 2018). "Meanwhile, quercetin-induced upregulation of Sirt1 enhances AMPK activity and decreases NADPH production, thus suppressing the hyperglycemia-induced oxidant damage in HUVECs." (PMID 28546854, 2017). "AMPK activates SIRT1 by increasing its substrate, NAD+, but this interaction is disrupted by hyperglycemia and oxidative stress." (PMID 26491232, 2015). "Podocyte apoptosis is aggravated by hyperglycemia and increased production of ROS and AGE, which in turn enhances FOXO4 acetylation and suppresses SIRT1 expression." (PMID 26491232, 2015). "In DKD, podocyte apoptosis is aggravated by hyperglycemia via increasing the production of advanced glycation end products (AGEs), which in turn increases FOXO4 acetylation and suppresses SIRT1 expression." (PMID 25346724, 2014). "This scenario of hyperglycemia and SIRT1 suppression likely occurs in the diabetic milieu where prolong hyperglycemia leads to AGE formation, and AGE reduces SIRT1 expression." (PMID 21858169, 2011). "This article observed the effects of hyperglycemia, the role of SIRT1 in podocyte protection, and the therapeutic potential of BF175 as a SIRT1 agonist, revealing the key role of SIRT1 in podocyte protection and the potential application of BF175 as a SIRT1 agonist in the treatment of DKD." (PMID 40862124, 2025). "The figure shows the transition from normal physiology to hyperglycemia and diabetic nephropathy, highlighting increased CD38- and PARP1-mediated NAD+ consumption, compensatory NAMPT upregulation, and subsequent SIRT1 depletion leading to mitochondrial dysfunction and renal injury." (PMID 41470091, 2025). "In addition, formononetin protects diabetic rats from hyperglycaemia-induced neuronal damage by controlling hyperglycaemia and upregulating NGF and Sirt1 in nerve tissues." (PMID 41181709, 2025). "In view of evidence on the correlation of the glycemic status of the organism with SIRT1 level, we systematically assessed basal astrocyte SIRT1 secretion in the BBB model constructed in three different glycemic backgrounds (hypo-, normo-, and hyperglycemia)." (PMID 37511397, 2023). "We confirmed the hindering effect of LPS-induced neuroinflammation and the boosting effect of RSV on the level of SIRT1 secreted by astrocytes in the BC of the BBB in all glycemic backgrounds, corresponding to three extreme glycemic conditions: hypo-, normo-, and hyperglycemia." (PMID 37511397, 2023). "Here, we addressed the regulation of SIRT1 secretion by astrocytes within the blood–brain barrier (BBB) in different glycemic backgrounds (hypo-, normo-, and hyperglycemia) in response to LPS-induced neuroinflammation and subsequent resveratrol (RSV) treatment." (PMID 37511397, 2023). "The results of our experiments are in line with the literature, where SIRT1 secretion in hypoglycemia was shown to be higher than in normoglycemia and in hyperglycemia to be lower than in normoglycemia." (PMID 37511397, 2023). "Furthermore, resveratrol, an activator of SIRT1, mimicked the anti-senescence action of GW501516 in hyperglycemia-exposed ARPE-19 cells, indicating that PPARδ inhibits cellular senescence by upregulating SIRT1." (PMID 35740104, 2022). "In conclusion, the CDK5-NGF/Sirt1 regulating axis may be the novel pathway to prevent DN progression and TFP5 may be a promising compound to improved hyperglycemia induced DN." (PMID 35874807, 2022).
Hyperglycemia (continued). "In addition, the combination effectively reversed the hyperglycemia-induced endothelial dysfunction in diabetic rats and regulated the expression of eNOS, 3-nitrotyrosine, VCAM-1, CD31 and SIRT-1 markers." (PMID 36496468, 2022). "In agreement with our proposal, previous studies have shown that MA ingredients, including Apigenin, luteolin, quercetin, ferulic acid, chlorogenic acid, isoorientin, naringenin, and resveratrol, ameliorate hyperglycemia and hyperlipidemia through activation of the AMPK signaling pathway and SIRT1." (PMID 36160451, 2022). "In conclusion, TFP5 treatment protects the kidney from hyperglycemia-induced damage by CDK5-NGF-Sirt1 regulation axis, and NGF and Sirt1 may be the novel target for DN." (PMID 35874807, 2022). "Therefore, caloric restriction promotes the appropriate response of pancreatic beta cells to hyperglycemia by inhibiting SIRT4 and activating SIRT1." (PMID 34899370, 2021). "Collectively, we demonstrated that melatonin could attenuate hyperglycemia-stimulated oxidant stress and apoptosis damage in CMECs via an AMPK/SIRT1 signaling dependent pathway." (PMID 34336116, 2021). "Indeed, in cell lines derived from human pancreatic beta cells or an insulinoma, hyperglycemia-induced NADPH oxidase activity, via p38, has been found to suppress transcription of the USP22 gene, and thereby down-regulate protein expression of Sirt1." (PMID 35052168, 2021). "Moreover, hyperglycemia in NIDDM is a hazardous issue that disturbs the genetic expression responsible for insulin secretion, e.g., sirtuin-1 (Sirt-1) and glucose transporter-2 (GLUT-2), in β-cells." (PMID 34833928, 2021). "Finally, SIRT1 and SIRT3 are involved in oxidative stress management: SIRT1 protects, through activation of FOXO1, cells against hyperglycemia-induced oxidative stress, whereas SIRT3 protects pancreatic cells in mice against palmitate-induced stress." (PMID 33806509, 2021). "Ginkgolide B treatment restored reduced expression of SIRT1, HO-1, and p-PMPK by hyperglycemia." (PMID 32952955, 2020). "Further, molecular docking results indicated that SIRT1 may be bound to PHL directly, which implies that PHL protected cardiac cells from hyperglycemia by targeting SIRT1." (PMID 31076562, 2019). "This direct lack of NAD+ by hyperglycaemia, is a rate limiting step for SIRT1 activity, as without this co-factor, SIRT1 is unable to deacetylate its targets." (PMID 30696833, 2019). "In addition, we found that hyperglycemia increased the expression of miRNA-30 family, in particular miRNA-30b that altered NSC differentiation via down regulation of its target, Sirt1 in NSCs." (PMID 28798665, 2017). "Our findings suggest that hyperglycemia and a deficit in vascular SIRT1 per se are not sufficient to prematurely shorten vascular telomeres." (PMID 26346823, 2015). "Hyperglycemia decreases AMPK expression, leading to reduced SIRT1 expression." (PMID 26491232, 2015). "When SIRT1 or the deacetylase inactive version of SIRT1 (H363Y) were over expressed in muscle, there was no alteration of the insulin resistance that occurs with 5h of hyperglycaemia." (PMID 25798922, 2015). "Secondly, although hyperglycemia leads to blunted SIRT1 and telomere shortening, we have shown in vivo that hyperglycemia and a deficit in vascular SIRT1 per se are not sufficient to prematurely shorten vascular telomeres." (PMID 26346823, 2015). "Although SIRT1 depletion and hyperglycemia have previously been shown to independently accelerate telomere shortening, our results have shown that hyperglycemia and blunted vascular SIRT1 in vivo were not sufficient to prematurely shorten arterial telomeres." (PMID 26346823, 2015). "The absence of SIRT1 increases the expression of p66Shc and promotes hyperglycemia-induced endothelial dysfunction." (PMID 24763109, 2014).